DYSF (dysferlin)
Diseases named in the same sentence as DYSF in open-access papers (continued):
Sharing a sentence is not in itself a finding about the gene and the disease.
distal myopathy (17 papers, 2007 to 2024). Distal myopathy refers to a group of muscle diseases which share the clinical pattern of predominant weakness and atrophy beginning in the feet and/or hands. "While Miyoshi distal myopathy (LGMD type 2B (LGMD2B)/R2, dysferlin mutation) is the most common distal myopathy." (PMID 35198268, 2022). "Dysferlin (DYSF, encoding dystrophy‐associated fer‐1 like protein) is associated with skeletal muscle repair, and a defect in DYSF results in limb‐girdle muscular dystrophy type 2B and distal myopathy." (PMID 33410284, 2021). "Dysferlinopathies are caused by mutations in the DYSF gene and patients may present with proximal or distal myopathy." (PMID 27666772, 2016). "Other groups described patients with early-onset and late-onset distal myopathies preferentially involving the calf muscles who had normal dysferlin expression." (PMID 23050857, 2012).
muscle disorders (12 papers, 2013 to 2025). "Mutations in Dysferlin lead to Limb Girdle Muscular Dystrophy 2B (LGMD2B), an inherited, progressive and incurable muscle disorder." (PMID 24244862, 2013).
cardiomyopathy (11 papers, 2011 to 2026). A disease of the heart muscle or myocardium proper. "It has been proposed that dysferlin promotes cardiomyocyte repair, and that dysferlin deficiency leads to cardiomyopathy." (PMID 21816046, 2011). "The data indicated that dysferlin deficiency and disorders of the Z-line protein and transcription factors, especially under mechanical stress, could lead to cardiomyopathy." (PMID 41517735, 2026). "Previously, we demonstrated that a combined deficiency in dysferlin and dystrophin results in the development of a pronounced early-onset cardiomyopathy resembling that seen in DMD patients, in contrast to a mild, slowly progressing cardiac manifestation in mdx mice." (PMID 22132688, 2011). "Transgenic mice deficient in dysferlin exhibited changes to the protein composition within the Z-disc, which would, in part, explain why the lusitropic response is compromised and why genetic mutations of dysferlin can also lead to the development of cardiomyopathies." (PMID 31520263, 2019). "Interestingly, it was recently reported that DYSF deficiency leads to increased susceptibility to coxsackievirus B3 (CB3)-induced cardiomyopathy in C5-deficient A/J mice and suggested an important mechanism of DYSF cleavage by viral proteases underpinning cardiac dysfunction." (PMID 31601172, 2019). "In addition, dysferlin deficiency also causes the development of cardiomyopathy." (PMID 22110769, 2011). "In addition to LMNA, mutations to CAV3, ACTA1, ACTC1, DYSF, and DSG2 are linked to cardiomyopathies and encode proteins that are long-lived in the heart." (PMID 37162946, 2023). "Here, we present an individual with a combination of cardiomyopathy and limb-girdle type muscular dystrophy where whole exome sequencing identified myoferlin (MYOF)—a member of the Ferlin protein family and close homolog of DYSF—as the most likely candidate gene." (PMID 31297131, 2019).
Duchenne muscular dystrophy (10 papers, 2008 to 2025). Duchenne muscular dystrophy (DMD) is a neuromuscular disease characterized by rapidly progressive muscle weakness and wasting due to degeneration of skeletal, smooth and cardiac muscle. "Chan also reported an increased risk of RM in patients with some hereditary neuromuscular diseases, such as Duchenne muscular dystrophy (DMD)/Becker muscular dystrophy (BMD), fukutin-related protein, dysferlin, γ-sarcoglycans, and anoctamin 5 deficiency-associated muscular atrophy." (PMID 33014933, 2020). "Oxidative stress has been implicated in several skeletal muscle degenerative diseases, such as Duchenne muscular dystrophy (DMD), facioscapulohumeral dystrophy (FSHD), laminopathy and dystrophies related to mutation in collagen VI and dysferlin genes." (PMID 33801315, 2021). "Finally, the large size of the mutated genes such as dystrophin (14 kb mRNA) in Duchenne Muscular Dystrophy (DMD) or dysferlin (6.2 kb mRNA) in limb–girdle muscular dystrophy type 2B (LGMD2B) and Miyoshi myopathy, challenges classical gene replacement therapies." (PMID 35910413, 2022).
calpainopathy (9 papers, 2019 to 2026). "Secondary dysferlin loss in calpainopathy has been reported previously." (PMID 38812636, 2024). "A secondary dysferlin reduction has been reported in primary caveolinopathy and calpainopathy." (PMID 36012197, 2022). "The global prevalence of LGMDs is estimated to range from 0.8 to 6.9 per 100,000 individuals, with CAPN3-related calpainopathy (LGMD2A/R1) emerging as the most common subtype, followed by DYSF-related LGMD (LGMDR2)." (PMID 40870035, 2025).
progressive muscular dystrophy (8 papers, 2010 to 2023). "We also examined the molecular behavior of GFP-wild-type MG53 during sarcolemmal repair in dysferlin-deficient mice which show progressive muscular dystrophy, and found that GFP-MG53 accumulated at the wound similar to wild-type mice." (PMID 23145354, 2012). "The association between the development of RSC in similar muscle groups to those most severely affected by the progressive muscular dystrophy suggested that these neoplasms developed from abnormal regeneration of the skeletal muscle exacerbated by the dysferlin mutation." (PMID 21853140, 2011). "Mutations in dysferlin lead to a progressive muscular dystrophy." (PMID 21079765, 2010). "One such mouse model is the Dysftm1Kcam strain, which was generated using a targeting vector to replace a 12-kb region of the dysferlin gene and which features a progressive muscular dystrophy." (PMID 26464793, 2015). "This strain is also characterized by a progressive muscular dystrophy homologous to limb-girdle muscular dystrophy type 2B, due to a retrotransposon insertion in the dysferlin gene." (PMID 21853140, 2011). "The mice expressing these elevated levels of dysferlin were kyphotic with an irregular gait and a non-necrotic progressive muscular dystrophy characterized by marked atrophy and weakness." (PMID 22666441, 2012).
atherosclerosis (7 papers, 2019 to 2026). A disease characterized by the build-up of fatty material and calcium deposition in the arterial wall resulting in partial or complete occlusion of the arterial lumen. "In peripheral blood leukocytes of patients with atherosclerosis, hypermethylation of the DYSF promoter upregulates its expression, promoting monocyte activation; it also enhances monocyte activation by upregulating selectin L(SELL)." (PMID 41526548, 2026). "To further document the role of dysferlin in atherosclerosis, we examined plaque burden in the aortic sinus of mice after both 5 and 9 months of HFD." (PMID 34366880, 2021). "Atherosclerosis is a complex process that involves multiple cells types that incidentally express dysferlin." (PMID 34366880, 2021). "Moreover, DYSF promotes monocyte activation, enhancing its phagocytosis, adhesion, and migration, thus contributing to the formation of necrotic cores in atherosclerosis and playing an important role in atherosclerotic cardiovascular disease." (PMID 40620701, 2025). "Dysferlin (DYSF) is an important molecule related to monocyte differentiation and inflammatory cytokine release, while the hypermethylation of DYSF’s promoter can upregulate its expression and facilitate the activation of monocytes, which further promotes the pathogenesis of atherosclerosis." (PMID 36552836, 2022). "These mice were fed a high fat diet to increase atherogenic plasma lipids, and we unexpectedly observed that loss of dysferlin does not increase basal or hyperlipidemia-accelerated atherosclerosis." (PMID 34366880, 2021). "To test whether dysferlin protects the vasculature against atherosclerosis, we generated dysferlin-null mice on an apolipoprotein E-null (ApoE) background supplemented with a high fat diet (HFD) for 5 and 9 months (mo) to induce hyperlipidemia." (PMID 34366880, 2021). "Hence, in multiple sections of the aorta, the loss of dysferlin did not impact atherosclerosis development." (PMID 34366880, 2021). "In all cases, loss of dysferlin did not significantly affect basal or dyslipidemia-induced atherosclerosis, which suggests that dysferlin does not protect against atherosclerosis in distal sections of the aorta." (PMID 34366880, 2021). "Our study suggests that dysferlin does not protect against atherosclerosis or participate in cholesterol absorption blockade but regulates basal plasma lipoprotein composition." (PMID 34366880, 2021). "To test this hypothesis, we generated dysferlin-null mice lacking apolipoprotein E (ApoE), a common model of atherosclerosis, dyslipidemia and endothelial injury when stressed with a high fat, and cholesterol-rich diet." (PMID 34366880, 2021).
polymyositis (7 papers, 2013 to 2025). A rare idiopathic inflammatory myopathy characterized by symmetric proximal muscle weakness and elevated muscle enzymes. "Interestingly, we detected reduced dysferlin levels in patients with inflammatory myopathies (polymyositis, inclusion body myositis) treated with steroids (unpublished data)." (PMID 23406536, 2013).
dilated cardiomyopathy (5 papers, 2012 to 2026). Cardiomyopathy which is characterized by dilation and contractile dysfunction of the left and right ventricles. "On the other side, LGMD2B, caused by mutation in dysferlin gene, is known for the fluctuating onset of dilated cardiomyopathy." (PMID 34066119, 2021). "Dysferlin-knockout (KO) mice develop a dilated cardiomyopathy characterized by decreased left ventricular ejection fraction and reduced heart rate." (PMID 40860890, 2025). "Loss of DYSF causes death of cardiomyocytes, notably in aging hearts, leading to dilated cardiomyopathy and heart failure in patients with LGMD2B." (PMID 34466782, 2021).
sarcoglycanopathies (5 papers, 2015 to 2026). "A study on 105 Chinese patients, Showed that the most common subtype was LGMDR2 dysferlin related, and LGMDR3 α -sarcoglycan related is the most frequent type of sarcoglycanopathies." (PMID 31937337, 2020).
dermatomyositis (4 papers, 2020 to 2025). Dermatomyositis (DM) is a type of idiopathic inflammatory myopathy characterized by evocative skin lesions and symmetrical proximal muscle weakness. "For example, previous research has shown that dermatomyositis (DM) and its disease progression are at least partially associated with increased dysferlin levels as well as increased polyol pathway activity." (PMID 32024865, 2020). "For example, upregulation of DYSF expression plays a key role in inflammatory cell infiltration and muscle damage in dermatomyositis and idiopathic inflammatory myopathy." (PMID 40620701, 2025).
dyslipidemia (4 papers, 2019 to 2024). "We have recently demonstrated in typically mild dysferlin- and dystrophin-deficient mouse models that increased plasma cholesterol levels severely exacerbate muscle wasting, and that DMD patients display primary dyslipidemia characterized by elevated plasma cholesterol and triglycerides." (PMID 36447272, 2022).
autoimmune disease (3 papers, 2023 to 2025). A disorder resulting from loss of function or tissue destruction of an organ or multiple organs, arising from humoral or cellular immune responses of the individual to their own tissue constituents. "However, dysregulation of DYSF expression is closely associated with various hereditary myopathies and autoimmune diseases." (PMID 40620701, 2025). "The dysregulation of DYSF expression is closely related to many hereditary myopathies and autoimmune diseases." (PMID 37152368, 2023). "Dysferlin deletion is also closely related to the occurrence and development of autoimmune diseases." (PMID 37525657, 2023).
rhabdomyolysis (3 papers, 2022 to 2025). Necrosis or disintegration of skeletal muscle often followed by myoglobinuria. "Genetic testing with a panel of genes associated with rhabdomyolysis confirmed presence of the “A-” G6PD variant (c.[202G>A; 376A>G] p.[Val68Met; Asn126Asp]) and a heterozygous variant of unknown significance in the dysferlin gene (DYSF c.4510G>A p.Val1504Ile)." (PMID 35287717, 2022).
sarcoma (3 papers, 2011 to 2022). A usually aggressive malignant neoplasm of the soft tissue or bone. "Significantly, the simultaneous loss of dystrophin and dysferlin or dystrophin and calpain-3 leads to a drastically increased sarcoma propensity, which is compatible with an additive TS function of these MD-related proteins." (PMID 35790299, 2022). "Notably, dysferlin-deficiency on the mixed C57BL/10 x B6C3Fe background resulted in a predominant abdominal wall location of sarcomas." (PMID 21533183, 2011). "Thus, additional loss of both dysferlin and calpain-3 in dystrophin-deficient mdx mice dramatically reduced sarcoma latency." (PMID 21533183, 2011). "While the spontaneous occurrence of RMS has been previously reported in mdx mice and in addition in mice deficient of α-sarcoglycan (Sgca −/−, a model for the human LGMD2D), this is the first report of sarcomas in mice lacking dysferlin, calpain 3, or Large." (PMID 21533183, 2011).
Alzheimer disease (2 papers, 2023 to 2025). A progressive, neurodegenerative disease characterized by loss of function and death of nerve cells in several areas of the brain leading to loss of cognitive function such as memory and language. "As a parallel, DYSF aggregates are seen in association with neuritic plaques in Alzheimer disease, and these aggregates are hypothesized to form due to the inability of neurons to repair membrane damage." (PMID 40352730, 2025). "In the central nervous system, dysferlin has been observed to accumulate in endothelial cells near sclerosis lesions, as well as within amyloid-beta plaques in people with Alzheimer’s disease." (PMID 37538852, 2023).
dystroglycanopathies (2 papers, 2014 to 2023). "Here we have characterized the contribution of dysferlin-deficiency to the pathology of dystroglycanopathy using double mutant mice for dysferlin and α-DG glycosylation." (PMID 25198651, 2014). "To generate double mutant mice, we crossed dysferlin-deficient SJL/L mice (dysferlinsjl/sjl) with two distinct dystroglycanopathy models, fukutin-deficient or Large-deficient mice." (PMID 25198651, 2014). "To investigate this question, we crossed dysferlin-deficient mice with two distinct dystroglycanopathy mouse models and analyzed the resultant phenotypes." (PMID 25198651, 2014). "To investigate contributions of dysferlin deficiency to the pathology of dystroglycanopathy, we have crossed dysferlin-deficient dysferlinsjl/sjl mice to the fukutin-knock-in fukutinHp/− and Large-deficient Largemyd/myd mice, which are phenotypically distinct models of dystroglycanopathy." (PMID 25198651, 2014). "Furthermore, the exact contribution of dysferlin and dysferlin-interacting proteins to the pathology of dystroglycanopathy is not known." (PMID 25198651, 2014).
dystrophinopathy (2 papers, 2017 to 2021). "Enhanced membrane repair involving myoferlin, dysferlin, and annexins has been found to be accompanied by a robust inflammatory response in the progressive neuromuscular disorder dystrophinopathy." (PMID 34957301, 2021).
Myalgia (2 papers, 2022 to 2025). "Second, APC, ENO3, ACAD9, RNASEH1, FKTN, DYSF, and ATP2A1 are associated with Myalgia." (PMID 40831500, 2025).
protein deficiency (2 papers, 2020 to 2024). "An 18-year-old woman presented with progressive weakness of limbs, persistent elevated serum creatine kinase, myogenic damages in electromyography, and dysferlin protein deficiency in muscle biopsy." (PMID 33031319, 2020).
renal cell carcinoma (2 papers, 2022 to 2025). "Interestingly, patients with renal-cell carcinoma and high DYSF gene expression levels presented with a better survival rate compared with renal-cell carcinoma patients with low DYSF expression." (PMID 35790299, 2022).
Sepsis (2 papers, 2020 to 2023). Sepsis is defined as life-threatening organ dysfunction caused by a dysregulated host response to infection. "In conclusion, we used bioinformatics methods to screen three key macrophage-related genes, SGK1, DYSF and MSRB1, which have a good diagnostic effect on sepsis-induced ARDS." (PMID 37336980, 2023).
acquired aplastic anemia (1 paper, 2014). Acquired aplastic anemia is a rare, serious blood disorder, due to failure of the bone marrow to produce blood cells. "Screening other macrocytic blood disorders revealed the presence of dysferlin in the RBC of four of eight acquired aplastic anemia patients but not in any of the other 11 patients with various bone marrow failure disorders." (PMID 24454878, 2014).
aplastic anemia (1 paper, 2014). Anemia resulting from bone marrow failure (aplastic or hypoplastic bone marrow). "Western blot analysis of RBC membrane preparations show low to moderate levels of dysferlin in these acquired aplastic anemia patients compared to DBA patients." (PMID 24454878, 2014). "Interestingly, one of these aplastic anemia patients has slightly higher eADA activity and a copy number neutral 5q loss of heterozygosity in the region of the RPS14 gene, raising the possibility of a functional connection between RP haploinsufficiency and dysferlin accumulation in RBCs." (PMID 24454878, 2014). "Interestingly, of all the samples tested, dysferlin was not in any other inherited bone marrow failure syndrome tested, however it was found on the RBC of four of the eight acquired aplastic anemia patients." (PMID 24454878, 2014).
Autoimmunity (1 paper, 2014). The occurrence of an immune reaction against the organism's own cells or tissues. "This may reflect the propensity of SJL/J mice to develop autoimmunity with age but may also be a manifestation of dysferlin deficiency in these mice." (PMID 24818014, 2014).
Blindness (1 paper, 2012). Blindness is the condition of lacking visual perception defined as a profound reduction in visual perception. "Our findings are supportive of the unique properties of AAV5 to express a 6.5 kb cDNA producing full length protein but the mechanism for expression of the dysferlin gene pointed in a different direction than reported for the series of retinal genes protecting against blindness." (PMID 22720081, 2012).
Bradycardia (1 paper, 2023). A slower than normal heart rate (in adults, slower than 60 beats per minute). "Cardiac abnormalities were observed in three patients with LGMD-R2-dysferlin-related, including one with decreased diastolic function of the LV, one with high voltage in the LV and one with bradycardia." (PMID 37974208, 2023).
Charcot-Marie-Tooth disease (1 paper, 2024). An inherited degenerative disorder involving the peripheral nerves. "Genetic testing ruled out Charcot-Marie-Tooth disease but identified a pathogenic variant in the DYSF gene." (PMID 39376872, 2024).
Chorea (1 paper, 2022). Chorea (Greek for 'dance') refers to widespread arrhythmic involuntary movements of a forcible, jerky and restless fashion. "It is suggested that chorea may be associated with altered expression of the brain isoform of dysferlin." (PMID 35273475, 2022).
clear cell renal cell carcinoma (1 paper, 2021). "For instance, dysferlin was described to be a proteomic marker of muscle dystrophies and introduced as a promising prognostic biomarker in clear cell renal cell carcinoma." (PMID 34439329, 2021).
cystic fibrosis (1 paper, 2012). Autosomal recessive disorder caused by pathogenic variants in the CFTR gene (cystic fibrosis transmembrane conductance regulator), which encodes a chloride and bicarbonate channel expressed in epithelial cells, and follow the diagnosis criteria. "However, in searching for strategies to intervene with misfolded dysferlin, we identified similarities to approaches used to unfold mutated cystic fibrosis transmembrane regulators (CFTR), the membrane protein affected in cystic fibrosis." (PMID 23185377, 2012).